CAPSL (calcyphosine like)
Synonyms: MGC26610
Tractability: Antibody: the Human Protein Atlas places it where antibodies can reach.
Gene: Protein-coding gene on chromosome 5 (35,904,288 to 35,938,779, reverse strand). Ensembl gene ENSG00000152611.
Subcellular location: Cytoplasm
Subcellular location (Human Protein Atlas): Microtubules; Nucleoplasm; Primary cilium; Cytokinetic bridge; Plasma membrane
Gene Ontology:
Molecular function: calcium ion binding
Cellular component: cytoplasm; organelle
Genetic constraint (gnomAD): Loss-of-function variants: 16 observed, 20.77 expected, observed/expected ratio (o/e) 0.77, 90% interval 0.52 to 1.17. The upper end of that interval is the gene's LOEUF score, 1.17, which puts it in group 5 of 6, group 1 being the genes least tolerant of losing a copy. Missense variants: 278 observed, 263.92 expected, observed/expected ratio (o/e) 1.05, 90% interval 0.95 to 1.16. Synonymous variants: 101 observed, 92.41 expected, observed/expected ratio (o/e) 1.09, 90% interval 0.93 to 1.29.
Homologues: Orthologues: chimpanzee CAPSL (99% identical), macaque CAPSL (99% identical), rabbit CAPSL (96% identical), pig CAPSL (95% identical), mouse Capsl (95% identical), guinea pig CAPSL (93% identical), rat Capsl (89% identical), tropical clawed frog capsl (81% identical), zebrafish capslb (76% identical), Drosophila melanogaster CG10126 (50% identical), Drosophila melanogaster CG31345 (49% identical). Paralogues in human: CAPS (48% identical), CAPS2 (30% identical), EFCAB6 (19% identical), PHF24 (12% identical), SPATA21 (11% identical).
Diseases named in the same sentence as CAPSL in open-access papers:
CAPSL is named in the same sentence as 7 diseases in open-access papers, as found by Europe PMC text mining. Sharing a sentence is not in itself a finding about the gene and the disease. The quoted sentences say what the papers report.
multiple symmetric lipomatosis (2 papers, 2019 to 2024). A rare subcutaneous tissue disease characterized by growth of symmetric non-encapsulated masses of adipose tissue mostly around the face and neck with variable clinical repercussions (e.g. reduced neck mobility, compression of respiratory structures). "In 2019, Julia Schreml pointed out that CAPSL is a promising candidate gene for multiple symmetric lipomatosis (MSL), a rare adipose tissue disorder of largely unknown etiology." (PMID 39264149, 2024).
asthma (1 paper, 2024). "CAPSL (5p13) has been reported to be associated with PBC, T1D, asthma, and SLE." (PMID 38616254, 2024).
autoimmune disease (1 paper, 2024). A disorder resulting from loss of function or tissue destruction of an organ or multiple organs, arising from humoral or cellular immune responses of the individual to their own tissue constituents. "Among the susceptibility regions for autoimmune diseases, we evaluated the polymorphisms of four genes (IL7R, CAPSL, CD226, and CLEC16A) and found the SNPs within two of these genes, IL7R and CAPSL, to be significantly associated with AITDs." (PMID 38612837, 2024). "Studies indicate a link between CAPSL and the development of autoimmune diseases such as type 1 diabetes." (PMID 38612837, 2024). "These include Il-7 and its receptor Il7R, CD226, CAPSL, and CLEC16A, which appear to be attractive candidates for further studies to explore the pathogenic mechanisms and potential therapeutic options for autoimmune diseases." (PMID 38612837, 2024).
autoimmune thyroid disease (1 paper, 2024). Inflammatory disease of the thyroid gland due to autoimmune responses leading to lymphocytic infiltration of the gland. "The aim of this study was to assess the prevalence of selected single-nucleotide polymorphisms (SNPs) of Il7R, CD226, CAPSL, and CLEC16A genes in children and adolescents with autoimmune thyroid diseases, and in the control group." (PMID 38612837, 2024). "This study aimed to assess the prevalence of selected single-nucleotide polymorphisms (SNPs) of Il7R, CD226, CAPSL, and CLEC16A genes in children with autoimmune thyroid diseases." (PMID 38612837, 2024).
Familial exudative vitreoretinopathy (1 paper, 2024). Familial exudative vitreoretinopathy (FEVR) is a rare hereditary vitreoretinal disorder characterized by abnormal or incomplete vascularization of the peripheral retina leading to variable clinical manifestations ranging from no effects to minor anomalies, or even retinal detachment with blindness. "CAPSL point mutations in two families with familial exudative vitreoretinopathy (FEVR)." (PMID 39264149, 2024).
CAPSL also shares sentences with these, for which no sentence is quoted: Huntington disease (1 paper); type 1 diabetes (1).